PTGS1 (prostaglandin-endoperoxide synthase 1)
Description:
Dual cyclooxygenase and peroxidase that plays an important role in the biosynthesis pathway of prostanoids, a class of C20 oxylipins mainly derived from arachidonate ((5Z,8Z,11Z,14Z)- eicosatetraenoate, AA, C20:4(n-6)), with a particular role in the inflammatory response. The cyclooxygenase activity oxygenates AA to the hydroperoxy endoperoxide prostaglandin G2 (PGG2), and the peroxidase activity reduces PGG2 to the hydroxy endoperoxide prostaglandin H2 (PGH2), the precursor of all 2-series prostaglandins and thromboxanes. This complex transformation is initiated by abstraction of hydrogen at carbon 13 (with S-stereochemistry), followed by insertion of molecular O2 to form the endoperoxide bridge between carbon 9 and 11 that defines prostaglandins. The insertion of a second molecule of O2 (bis-oxygenase activity) yields a hydroperoxy group in PGG2 that is then reduced to PGH2 by two electrons. Involved in the constitutive production of prostanoids in particular in the stomach and platelets. In gastric epithelial cells, it is a key step in the generation of prostaglandins, such as prostaglandin E2 (PGE2), which plays an important role in cytoprotection. In platelets, it is involved in the generation of thromboxane A2 (TXA2), which promotes platelet activation and aggregation, vasoconstriction and proliferation of vascular smooth muscle cells (Probable). Can also use linoleate (LA, (9Z,12Z)- octadecadienoate, C18:2(n-6)) as substrate and produce hydroxyoctadecadienoates (HODEs) in a regio- and stereospecific manner, being (9R)-HODE ((9R)-hydroxy-(10E,12Z)-octadecadienoate) and (13S)- HODE ((13S)-hydroxy-(9Z,11E)-octadecadienoate) its major products (By similarity).
Synonyms: PGHS-1; COX1; PTGHS; COX3; PCOX1; PES-1; PGG/HS; PGHS1; PHS1
Tractability: Small molecule: an approved drug acts on it; a high-quality ligand is known; it belongs to a druggable protein family. Antibody: UniProt places it where antibodies can reach, with medium confidence; UniProt predicts a signal peptide or a membrane-spanning region. PROTAC: its protein half-life has been measured; a small molecule that binds it is known. Other modalities: an approved drug acts on it.
Target class: Enzyme; Oxidoreductase
Chemical probes: SC-560 (high quality)
Safety:
Unwanted effects reported when the protein is acted on. In parentheses: how it was acted on, where the effect was seen, and who reports it.
Decrease, Population growth rate (inhibition; source: AOP-Wiki)
Reduced, Reproductive Success (inhibition; source: AOP-Wiki)
dyspepsia (inhibition; renal, pulmonary, gastrointestinal; source: Bowes et al. (2012))
gastric bleeding (inhibition; renal, pulmonary, gastrointestinal; source: Bowes et al. (2012))
Increased Mortality (inhibition; source: AOP-Wiki)
N/A, Reproductive failure (inhibition; source: AOP-Wiki)
pulmonary bleeding (inhibition; renal, pulmonary, gastrointestinal; source: Bowes et al. (2012))
renal dysfunction (inhibition; renal, pulmonary, gastrointestinal; source: Bowes et al. (2012))
Acute coronary syndrome (source: ClinPGx)
Gene: Protein-coding gene on chromosome 9 (122,370,530 to 122,395,705, forward strand). Ensembl gene ENSG00000095303.
Subcellular location: Microsome membrane; Endoplasmic reticulum membrane
Subcellular location (Human Protein Atlas): Golgi apparatus; Vesicles
Pathways (Reactome):
Metabolism: COX reactions; Synthesis of Prostaglandins (PG) and Thromboxanes (TX)
Gene Ontology:
Molecular function: prostaglandin-endoperoxide synthase activity; protein binding; heme binding; oxidoreductase activity, acting on paired donors, with incorporation or reduction of molecular oxygen; peroxidase activity
Biological process: cyclooxygenase pathway; prostaglandin biosynthetic process; regulation of blood pressure; cellular oxidant detoxification; prostanoid biosynthetic process; response to oxidative stress
Cellular component: cytoplasm; extracellular exosome; endoplasmic reticulum membrane; neuron projection; endoplasmic reticulum lumen; photoreceptor outer segment
Genetic constraint (gnomAD): Loss-of-function variants: 43 observed, 67.6 expected, observed/expected ratio (o/e) 0.64, 90% interval 0.5 to 0.82. The upper end of that interval is the gene's LOEUF score, 0.82, which puts it in group 3 of 6, group 1 being the genes least tolerant of losing a copy. Missense variants: 709 observed, 822.05 expected, observed/expected ratio (o/e) 0.86, 90% interval 0.81 to 0.92. Synonymous variants: 298 observed, 314.27 expected, observed/expected ratio (o/e) 0.95, 90% interval 0.86 to 1.04.
Homologues: Orthologues: chimpanzee PTGS1 (99% identical), macaque PTGS1 (98% identical), pig PTGS1 (91% identical), rabbit PTGS1 (91% identical), dog PTGS1 (89% identical), mouse Ptgs1 (89% identical), rat Ptgs1 (88% identical), guinea pig PTGS1 (83% identical), tropical clawed frog ptgs1 (70% identical), zebrafish ptgs1 (67% identical). Paralogues in human: PTGS2 (61% identical).
Diseases named in the same sentence as PTGS1 in open-access papers:
PTGS1 is named in the same sentence as 178 diseases in open-access papers, as found by Europe PMC text mining. Sharing a sentence is not in itself a finding about the gene and the disease. The quoted sentences say what the papers report.
asthma (22 papers, 2013 to 2026). "Clinical studies have revealed that certain transcriptional variants of PTGS1 are significantly upregulated in patients with asthma and that their expression levels are correlated with disease severity." (PMID 41557720, 2026). "Accumulating evidence shows that ITGB4, SEMA3D, FCAR (Fc fragment of IgA receptor), KIT (KIT proto-oncogene, receptor tyrosine kinase), PGLYRP1, IL17RB, BIRC5 and PTGS1 are associated with prognosis in asthma." (PMID 36837510, 2023). "Further investigation revealed several lipid-associated enzymes implicated in asthma pathogenesis to be encompassed by asthma-SEs (e.g., PTGS1, PTGS2, CYP24A1)." (PMID 33362848, 2020). "They re-analyzed genes in the AA pathway, and a new SNP of ALOX15 and PTGS-1 were found to be associated with AERD risk in comparison with asthma and healthy subjects." (PMID 30254660, 2018). "We identified 31 potential targets associated with AFB1 exposure and asthma, including PTGS2, ADRB2, CysLTR1, PTGS1, and others." (PMID 41557720, 2026). "proved that prostaglandin-endoperoxide synthase 1 (PTGS1), a lipid metabolism-associated enzyme, was implicated in epigenetic mechanisms underlying asthma pathogenesis in the airways." (PMID 38297226, 2024). "We identified initial evidence of asthma-associated Super-Enhancers encompassing genes encoding transcription factors (TP63) and enzymes regulating lipid metabolism (PTGS1)." (PMID 33362848, 2020). "LEPN observed in this EWAS is involved in angiogenesis, PTGS1 from isocyanate-asthma research is involved in angiogenesis regulation, and SALL1 and PDZRN3 observed in our GWAS on isocyanate biomarkers are also involved in angiogenesis and vascular morphogenesis, respectively." (PMID 34335698, 2021). "We identified 31 potential targets that may be associated with AFB1 exposure and asthma, including PTGS2, ADRB2, CysLTR1, PTGS1, and others, which play crucial roles in airway inflammation, smooth muscle contraction, immune regulation, and inflammatory mediator production." (PMID 41557720, 2026). "The expressions of PTGS1 and CYP3A4 were markedly increased in patients with rhinitis accompanied by asthma, while the expression of NR1I2 decreased synonym." (PMID 37741847, 2023). "Quercetin, luteolin, linolenic acid, adenosine, kaempferol, etc., were considered the potential core compounds, and PTGS2, ESR1, PTGS1, NOS2, AKT1, etc. were the main potential targets of BSYQ for asthma and IPF therapy." (PMID 35672815, 2022). "The PPI network, which had 31 nodes and 68 edges, was constructed using the intersection of AFB1 and asthma target genes In this study, PTGS2, ADRB2, MMP9, CysLTR1, and PTGS1 were the top five targets according to degree value, representing the hub targets of AFB1-induced asthma." (PMID 41557720, 2026). "Additionally, three asthma drugs undergoing clinical trials were found to interact with FCGR3A, despite targeting TNF (adalimumab and etanercept) and PTGS1/PTGS2 (indomethacin)." (PMID 37875944, 2023). "PTGS2 inhibition seemed to have a negative effect on both diseases, while PTGS1 was overrepresented only among targets of drugs contraindicated in asthma." (PMID 31705029, 2019). "Moreover, PTGS1 may be activated by IL-33 to catalyze the production of PG, thereby activating the ERK signaling pathway, such as serine phosphorylation of phospholipase A2, initiating AA release and prostaglandin synthesis, and promoting the development of asthma." (PMID 41557720, 2026).
atherosclerosis (8 papers, 2017 to 2023). A disease characterized by the build-up of fatty material and calcium deposition in the arterial wall resulting in partial or complete occlusion of the arterial lumen. "PTGS1 has clear vascular protective roles associated with the anti-thrombotic potential, vasoconstriction and the development of atherosclerosis and vascular inflammation." (PMID 35109845, 2022). "In rat atherosclerosis PCR array, Abca1, Bax, Bcl2, Bcl2a1, Cd44, Fabp3, Hbegf, Lypla1, Ptgs1, Selplg, Tgfb2, Tnc, and Vegfa had reverse trend between WT and MU groups, while the trends of Bcl2l1, Bid, Birc3, Cxcl1, Fas, Fn1, Itga2, Itga5, Lif, Nfkb1, Nr1h3, Ppard, and Sod1 were consistent." (PMID 34545275, 2021). "Most notably, PTGS1 rs10306194 carriers displayed higher values of three parameters, namely ccIMT progression [OR for accelerated progression = 1.90 (1.07–3.36), p = 0.029], presence of carotid plaque [OR = 1.79 (1.06–3.01), p = 0.026] and atherosclerosis severity score (p = 0.041)." (PMID 36690661, 2023).
colon cancer (8 papers, 2008 to 2025). "Therefore, PTGS1 may be regarded as another potential target for colon cancer prevention in high-risk groups." (PMID 35281077, 2022). "The current study didn’t observe evidence of interaction between variant alleles of SNPs in previously reported genes- ALOX15, IL16, MDR1, NFkB, PTGS1 and PTGS2- with aspirin only use and CRC or colon cancer risk." (PMID 29425227, 2018). "PTGS1 (also known as COX1), is a critical lipid metabolism molecular protein, and has been shown to be a pro-inflammatory mediator associated with an increased risk of colon cancer." (PMID 31215439, 2019). "Constitutive cyclooxygenase (COX) - 1 (gene PTGS1) is significantly related to the concentration of PGE2 in the colon and is highly expressed in colon cancer." (PMID 35281077, 2022). "Combining the expression trends of these genes in colon cancer and after aspirin treatment, we found that aspirin further upregulated NOX4, CXCL8, CXCL5, LIF, GDF15, and MMP13, while stimulated inhibition of IL2, NCF1, and PTGS1." (PMID 41425852, 2025).
colorectal cancer (7 papers, 2008 to 2025). A primary or metastatic malignant neoplasm that affects the colon or rectum. "In this context, it is interesting to note that PTGS1 methylation is frequent in prostate cancer, THY1 has been implicated as a candidate TSG in nasopharyngeal cancer and SST promoter methylation has been described in ∼90% of colorectal cancers." (PMID 18195710, 2008).
diabetes (7 papers, 2008 to 2025). "Several lines of evidence have also supported the role of the secondary genes FMO1 and ALOX1 having interaction with CYP3A4 and PTGS1 in diabetes mellitus." (PMID 36051390, 2022). "Of the top 15 proteins found by Cytoscape 3.6.1, 8, CAT and OGG1 (downregulated) and CASP3, COMT, CYP1B1, DPYD, NQO1, and PTGS1 (upregulated), were dysregulated in diabetes-related kidney disease." (PMID 34367469, 2021). "PTGS1 is prostaglandin endoperoxide synthase 1 that activates the prostaglandin pathway, and through TNF alpha signaling, the immune system will be upregulated or downregulated and will cause inflammation in type 2 diabetes mellitus." (PMID 36051390, 2022). "Therefore, it is logical to hypothesise that Cmpd17b treatment may be increasing the production of vasodilator prostanoids, likely via Ptgs1 to enhance endothelium-dependent relaxation in diabetes, which results in the compensatory downregulation of Ptgis gene expression." (PMID 32085666, 2020).
Hypertension (7 papers, 2012 to 2024). The presence of chronic increased pressure in the systemic arterial system. "Apart from Mmp11 which is a matrix metalloproteinases as Mmp2 we selected Ptgs1, Ptgs2 and Olr1 due to their possible relation to the vascular changes associated with hypertension." (PMID 28880918, 2017). "A series of studies in the Japanese population identified rs883484 located upstream of the PTGS1 gene as one of the genetic variants associated with CKD in individuals with metabolic syndrome, hypertension, and the general population." (PMID 35631221, 2022). "PTGS1 is one of the genes regulating blood pressure and arachidonic acid metabolism; it is one of the potential gatekeeper genes in programmed hypertension." (PMID 35631221, 2022).
melanoma (7 papers, 2015 to 2024). A malignant, usually aggressive tumor composed of atypical, neoplastic melanocytes. "We further validated that BRAFV600E melanoma depended on tumour-derived PGE2 to evade anticancer immunity by demonstrating that COX-deficient Ptgs1/Ptgs2−/− BRAFV600E melanoma, which lacks PGE2 production, failed to escape immune control." (PMID 38658748, 2024). "We used the staining protocol to assess cDC1 abundance in PGE2-producing control (COX-competent) BRAFV600E and Ptgs1/Ptgs2−/− (COX-deficient) BRAFV600E melanoma tumors." (PMID 29429633, 2018). "To test whether PGE2 impairs cDC1-mediated CD8+ T cell priming, we injected WT mice with PGE2-producing control or PGE2-deficient Ptgs1/Ptgs2−/− BRAFV600E melanoma cells engineered to express the model antigen ovalbumin (OVA)." (PMID 38658748, 2024). "Previously, it was described that type I interferon signaling, which overlaps with the innate immune response, is suppressed by PGE2 in COX-proficient melanomas, whereas the genetic ablation of Ptgs2 or Ptgs1 and -2 enables tumor recognition by the immune system." (PMID 32978520, 2020). "Tumor infiltration by cDC1s was confirmed by distance analyses after surface reconstruction of cDC1 profiles in confocal images, which revealed that cDC1 in Ptgs1/Ptgs2−/− BRAFV600E melanomas were located further away from the tumor margin and from CD31+ blood vessels than in control tumors." (PMID 29429633, 2018). "In addition to an increase in cDC1 and modest elevation of T cell populations, Ptgs1/Ptgs2−/− BRAFV600E melanomas showed a prominent early rise in NK1.1+CD3− cells, which was sustained over several days." (PMID 29429633, 2018). "Most mice that rejected Ptgs1/Ptgs2−/− cells were resistant to a subsequent challenge with unmodified parental BrafV600E melanoma cells, implying the development of immunity to shared target antigens and excluding a scenario of cancer immune privilege driven locally by tumor-derived prostanoids." (PMID 26343581, 2015).
ovarian carcinoma (7 papers, 2010 to 2024). A malignant neoplasm originating from the surface ovarian epithelium. "Therefore, whether simply acting on PTGS1 targets can obtain better anti-ovarian cancer effects will be a question we need to verify in the future." (PMID 38651149, 2024). "By screening 31 drugs with 110 targets, FNTA, HSPA5, NEU1, CCND1, CASP1, CASP3 were negatively correlated with ovarian cancer, and HMGCR, PLA2G4A, ITGAL, PTGS1, FNTB were positively correlated with ovarian cancer." (PMID 38651149, 2024). "Among them, FNTA, HSPA5, NEU1, CCND1, CASP1, CASP3 had a negative causal association with ovarian cancer development, and HMGCR, PLA2G4A, ITGAL, PTGS1, FNTB had a positive causal association with ovarian cancer development." (PMID 38651149, 2024).
Stroke (7 papers, 2010 to 2023). Sudden impairment of blood flow to a part of the brain due to occlusion or rupture of an artery to the brain. "Triflusal, a treatment for stroke re-occurrence, targets four genes (PTGS1 (also known as Cox-1), NOS2, NFKB1, and PDE10A) that together have more functional variants in the African population than in any other population (DRPAFR = 37%)." (PMID 29273096, 2017). "In our study, we revealed the association between clinical parameters (age, NIHSS score, atrial fibrillation), as well as SNPs in the PTGS1, ADRA2A, TBXA2R and PEAR1 genes, and laboratory indicators of platelet activity in ischemic stroke patients taking aspirin for secondary stroke prevention." (PMID 36289824, 2022).
breast carcinoma (6 papers, 2011 to 2025). "The up-regulation of PTGS1 in breast carcinomas compared to normal tissue is expected from current knowledge." (PMID 21812955, 2011). "Interestingly, MDH2 overexpression upregulated several genes associated with breast cancer metastasis (IL13RA2, MMP3, PTGS1, SYK, VCAN, and FLT1) and downregulated several genes associated with metastasis suppression (NOTCH3 and HTRA3)." (PMID 41179294, 2025). "PTGS1, also known as COX-1, is known to play a role in prostaglandin synthesis and has been shown to be linked to TNF-related apoptosis-inducing ligand (TRAIL)-induced apoptosis in a breast carcinoma cell line, MDA-MB-453." (PMID 28081256, 2017). "Specifically, we observed up-regulation of genes that drive breast cancer metastasis (IL13RA2, MMP3, PTGS1, SYK, VCAN, and FLT1) and downregulation of metastasis-associated suppressor genes (NOTCH3, and HTRA3)." (PMID 41179294, 2025). "Additionally, we noted the downregulation of SCD, coupled with the upregulation of PTGS1 and PTGSE, in tumor samples from some HER2‐positive breast cancer patients exhibiting secondary trastuzumab resistance compared to trastuzumab‐sensitive patients." (PMID 38460162, 2024).
Obesity (6 papers, 2021 to 2024). Accumulation of substantial excess body fat. "The mRNA expression of a cytochrome P450 gene CYP1B1, ALOX5 (which encodes 5-LOX), and PTGS1 (which encodes COX-1) was upregulated in individuals living with obesity." (PMID 35247847, 2022). "The mRNA expression of CYP1B1, ALOX5 and PTGS1 were upregulated in individuals with obesity." (PMID 38024342, 2023). "For the identified DEHGs for obesity, there were six previously reported genes (UGGT1, ANO6, MPEG1, PTGS1, CLU and IQGAP1) and two novel genes (LUZP6 and PLCB2) for obesity." (PMID 35568907, 2022). "In individuals living with obesity, 13-HODE was positively correlated with the expression of PTGS2, and PGD3 was positively correlated with PTGS1 and negatively correlated with PTGS2." (PMID 35247847, 2022). "In the renal cell carcinoma (RCC) group, the greatest increase is seen in RCC without comorbid obesity or smoking, as seen with upregulation of PTGS1, which aligns with current literature studying that COX-1 expression correlates with clinicopathological features of RCC." (PMID 39062733, 2024).